FUS (FUS RNA binding protein)
Diseases named in the same sentence as FUS in open-access papers (continued):
Sharing a sentence is not in itself a finding about the gene and the disease.
cancer (83 papers, 2008 to 2026). A tumor composed of atypical neoplastic, often pleomorphic cells that invade other tissues. "Genetic alterations of FUS, a multifunctional nuclear protein involved in several steps of RNA metabolism, can be associated with human diseases, such as cancer and neurodegenerative disorders." (PMID 34299185, 2021). "Conversely, high levels of FUS are associated with cancer and ALS, and moreover, are known genetic determinants of these diseases." (PMID 24204307, 2013). "Among genes present in the 16p11.2 amplicon only FUS has until now been reported as altered by somatic simple mutation in cancer (Cosmic v48 release)." (PMID 21151896, 2010). "We found that all three lncRNAs, i.e., RP11-33A14.1, RP11-423H2.3, and LAMTOR5-AS1, interacted with FUS, while the loss of FUS expression may contribute to cancer progression." (PMID 32117463, 2020). "We hypothesize that the efficiency may even be lower in vivo and is a bottleneck for generation of some cancers that require multiple genetic mutations for tumorigenesis, such as FUS-CHOP-driven tumors." (PMID 31427882, 2019). "Genetic alterations in FUS cause human diseases such as cancer and neurodegeneration." (PMID 25501833, 2014). "Additionally, we observed functional enrichment around transcriptional misregulation in cancer, a function that might be expected given the strong association of FUS with neoplastic pathologies." (PMID 37887305, 2023). "Taken together, this suggests SON, FUS, and ALDHA3 can be potential targets for the treatment of cancer-associated EMT." (PMID 39796712, 2024). "Motivated by our findings, we included in this review recent publications focusing on the RNA-binding activity of FUS, which has been related to different cancer types." (PMID 38473229, 2024). "The only known genetic alterations affecting TFCP2 in cancer are the recently discovered fusions to FUS and EWSR1 in atypical RMS." (PMID 38168093, 2024). "Fused in sarcoma (FUS) is a DNA/RNA binding protein that is dysfunctional in various malignant tumors." (PMID 37158824, 2023). "CHOP has been shown to promote cancer progression when fused with FUS/TLS or EWS protein by genomic rearrangement." (PMID 37685841, 2023). "We referred to previous studies and found that FUS participates in the regulation of various cancers." (PMID 36224753, 2022). "Abnormally formed FUS/EWS/TAF15 (FET) fusion oncoproteins are essential oncogenic drivers in many human cancers." (PMID 33674598, 2021). "FUS is a transcription factor and an RBP associated with several kinds of malignant tumours, and it was reported that the binding of FUS to AKT contributes to AKT nuclear translocation and activation." (PMID 34074294, 2021). "We identified several cancer-associated splicing factors as G4 sensitisers, including SRSF10, HNRNPM and the known G4-interactor FUS, which is overexpressed in several cancers." (PMID 31287417, 2019). "Of the many RBPs that bind to the KRAS 3′ UTR, AGO2, HuR (or ELAVL1), IGF2BP1/2/3, PUM2, EWSR1, TAF15, FUS, and TIA1 have been previously implicated in cancer." (PMID 26930719, 2016). "These included homozygous variants calls in genes related to cancer (BRCA1, APC, MEN1), congenital malformation syndromes (TCOF1), metabolic deficiencies (FBP1, HEXA), and neurological diseases (FUS, MLC1, DMD)." (PMID 26547235, 2015). "Select introns, such as two adjacent introns in FUS, were recurrently retained in cancers from many different tissues of origin." (PMID 26113877, 2015). "FUS was initially identified as a fusion oncoprotein, and thus, the early literature focused on the role of FUS in cancer." (PMID 25289647, 2014). "Several studies reported CHOP gene rearrangement and/or fusion with other genes (such as EWS-CHOP and TLS/FUS-CHOP) in tumors/cancer." (PMID 19558691, 2009). "The studies presented here suggest that the role played by FUS in specific cancer types may depend on the RNAs with which it is interacting in the cancer cells." (PMID 38473229, 2024).
cancer (continued). "Thus, FUS is a key protein in understanding the intersection of RNA biology, neurodegeneration, and cancer biology, and its behavior in LLPS provides significant insights into these diverse medical conditions." (PMID 39113127, 2024). "Bioinformatics analysis by ENCORI1 found that lncRNA NORAD binds with RBP FUS in cancer cells." (PMID 34307380, 2021). "These may include gene amplification, insertion, deletion or translocation (eg, FUS-CHOP or EWS-CHOP), as well as mutation in other cancer genes." (PMID 24695632, 2014). "The strong nuclear preference of EWS in most cell types in contrast to FUS and TAF15 may be connected to its more frequent mutation in human cancers were the oncoprotein is restricted to nuclear functions as an aberrant transcription factor." (PMID 18620564, 2008). "Interestingly, FUS interacts with several circRNAs within the context of different cancer types, which may be a result of the role that FUS plays during the back-splicing process of specific circRNAs." (PMID 38473229, 2024). "In our study, we found that FUS could interact with circTBC1D14 to generate SGs under hypoxic conditions, which contributed to changes in the subcellular localization of SGs and the maintenance of cancer cell homeostasis in response to stress." (PMID 36806670, 2023). "To better understand the mechanisms underlying the association of NUSAP1 overexpression and cancer aggressiveness, we used AP–MS to identify novel interactions between NUSAP1 and several proteins with described functions in R-loop biology and DDR, including DHX9, ILF2, HNRPC, FUS, and RBMX." (PMID 37047232, 2023). "In both groups of these cancers, the CREB-family member is activated by being incorporated in the protein encoded by the fusion and by being placed under the control of the EWSR1 or FUS promoter, both of which are transcriptionally active in the cells of origin of these tumors." (PMID 36313756, 2022). "This further highlight the putative functions of FUS and EWS in regulating genes encoding proteins associated with the RNA regulome and that deregulation of particular components of this program may be an important factor in cancer and neurological diseases." (PMID 26573619, 2015). "Interestingly, in both FUS-associated ALS and cancer, loss of heterozygosity of the FUS gene is never observed." (PMID 24204307, 2013). "Genes such as FENDRR, MALAT1, FUS, and CRNDE were found to be involved in numerous cancer-stage-cell processes." (PMID 40728857, 2025). "In this work, we demonstrated that several well-characterized IDRs including those from FUS, EWS and TAF15, promote the condensation of CARs on the T cell membranes, which leads to enhanced cytotoxicity toward low-antigen-expressing cancer cells." (PMID 41023404, 2025). "Thus, eIF4A3 and FUS may represent major pan-cancer therapeutic targets." (PMID 35729321, 2022). "Fused in sarcoma (FUS, a coactivator of NF-κB subunit RELA) was also regulated by SIX1 in cancer cells." (PMID 34513929, 2021). "Finally, there were only a few FUS mutations reported to influence DNA repair, thus it is possible that the majority of patients not carrying those were not at risk for cancer which could not be addressed in our sample size." (PMID 31682085, 2019).
cancer (continued). "It will be informative to extend FUS and EWS ChIP-seq profiling to other cell models to study the protein functions in more details and in relation to specific diseases involving FUS and EWS deregulation, such as cancer and neurodegenerative disorders." (PMID 26573619, 2015). "For example, AGO protein is an RBP that serves as a platform of mRNA and small RNA interactions, and the FET family RBPs, including FUS, EWSR1 and TAF15, play important roles in RNA editing and human cancers." (PMID 24714572, 2014). "The FET family proteins (FUS, EWSR1 and TAF15) are abundant and highly conserved RBPs involved in cancer biology and other diseases." (PMID 24714572, 2014). "A number of cancer-related genes are located in these two RARs: NUPR1, MVP, MAPK3, FUS, and PYCARD are located in RAR-G12 while ERBB2, GRB7, and PPP1R1B are located in RAR-G13." (PMID 22938721, 2012). "The regulatory effects of circRNAs on the function of FUS and other FET proteins may have potential for the development of therapies in various cancer types." (PMID 38473229, 2024). "The other benign or malignant tumor types harboring FUS or EWSR1 translocation show no gene amplification using FISH." (PMID 36555836, 2022). "Pathways derived from NOTCH3, PARD3, CACNA1A, MAX, RAD50, FUS and LMO2 were cancer-related." (PMID 34540367, 2021). "RBMX (RNA Binding Motif Protein X-Linked), NONO (Non-POU Domain Containing Octamer Binding) and FUS (FUS RNA Binding Protein) are the three RNA-binding proteins that have been demonstrated to be potential cancer drivers." (PMID 33202812, 2020). "In this regard, it is important to understand how both mutant and wild-type FUS activities may contribute to the progression of ALS and cancer." (PMID 24204307, 2013). "Moreover, FUS functions as an RBP of lncRNAs and has important impacts on cancer development." (PMID 35599603, 2022). "Moreover, we found some gene functions, such as Fused in Sarcoma (FUS, which may be part of transcriptional misregulation in cancer) and p27 (which we expect will become a member viral carcinogenesis), that can be used to complete the related pathways." (PMID 29321535, 2018). "ET743 also inhibits FUS-CHOP transcription factor binding to the promoters of different genes among CHOP, pentraxin 3 and fibronectin 1 to restore adipogenic differentiation in myxoid liposarcoma, a cancer against which ET743 entered into phase I/II clinical trials." (PMID 29921764, 2018).
neurological disorders (34 papers, 2012 to 2025). "Many protein condensates associated with neurological disorders, such as α-synuclein, FUS, and TDP-43 undergo a similar transition from the liquid-to-solid state." (PMID 39009833, 2024). "hnRNPA2/B1, hnRNPA1, and fused in sarcoma (FUS) are RBPs often associated with neurological diseases and, therefore, it is of the utmost importance to maintain RBP physiological levels in the nervous system." (PMID 36009412, 2022). "FUS mutations or pathological inclusions have been associated with neurological diseases including ALS, FTLD, and ET." (PMID 32307925, 2020). "This transition could either be due to the entanglement of biopolymers or stronger association of proteins leading to fibril formation as reported for many protein condensates associated with neurological disorders such as FUS, TDP-43, Tau, and hnRNPA1." (PMID 34944414, 2021). "This study suggests that FUS mutation leads to pleiotropic phenotypes beyond the nervous system, including alterations in lipid metabolism, which are important to consider in FUS-related neurological disorders." (PMID 37772684, 2023). "Aberrant expression, dysfunction and particularly the aggregation of a group of RNA-binding proteins, including TDP-43, FUS and RBM45, are associated with several neurological disorders." (PMID 37296572, 2023). "FUS is an essential RNA binding protein, which has been reported in nervous system diseases and human tumors." (PMID 35733138, 2022). "Primarily mutant FUS impairs neuronal survival and causes defects in dendritic growth and synaptic connectivity by interfering with the ability of FUS in DNA damage repair and RNA splicing, leading to neurological disorders." (PMID 31022909, 2019). "Aberrant expression, dysfunction and particularly aggregation of a group of RNA-binding proteins, including TDP-43, FUS and RBM45, are associated with neurological disorders." (PMID 30992467, 2019). "FUS interacts with several other RBPs, including FMRP and Survival Motor Neuron (SMN), two well-characterized RBPs that, similarly to FUS, are present in cytoplasmic RNA granules and are strongly linked to neurological diseases." (PMID 34290090, 2021). "Neuronal homeostasis may be dependent upon a complex balance between nuclear and extra-nuclear RNA processing events controlled by proteins such as SFPQ, HNRNPA2, U1 snRNP70, and FUS, a balance that, when disturbed, may contribute mechanistically to a wide range of neurological disorders." (PMID 28392072, 2017). "The identification of FUS mutations and accumulation of FUS within ubiquitin-positive neuronal cytoplasmic inclusions (NCI) in a portion of ALS cases led to the re-examination of other neurological diseases with NCI of unknown origin." (PMID 23046583, 2012). "Many genes play an important role, with TARDBP, SQSTM1, VCP, FUS, TBK1, CHCHD10, and most importantly, C9orf72 being critical genetic players in these neurological disorders." (PMID 33805659, 2021). "Mutations and abnormal expression of RNA-binding proteins have been reported to be engaged in different neurological diseases, including FMRP, TAR DNA binding protein 43 (TDP-43), Hu proteins, and FUS." (PMID 34833008, 2021). "The notion that FUS mislocalization is a widespread pathological event in sporadic ALS, but also in many other neurological diseases, prompted us to investigate the behavioral phenotype of FusΔNLS/+ mice." (PMID 34021132, 2021). "TARDBP, SQSTM1, VCP, FUS, TBK1, CHCHD10, and most importantly C9orf72, are the critical genetic players in these neurological disorders." (PMID 32116499, 2020). "On the other hand, we identified 11 and 26 common transcriptional regulators between FUS- and SOD1-ALS in our datasets and GSE106382 dataset, suggesting their involvement in many neurological diseases including ALS." (PMID 32967368, 2020).
neurological disorders (continued). "Numerous splicing factors identified here have been reported to have functions in neuronal differentiation, neurological diseases, or synaptic plasticity, such as ELAVL2, ZIC1, A2BP1 (official gene symbol Rbfox1), and FUS." (PMID 24758366, 2014). "Intriguingly, the perturbed nuclear localization and aggregation into discrete cytoplasmic foci exhibited by the ADAT3-V144M variant are reminiscent of other RNA binding proteins known to misfold and homooligomerize in neurological disorders, such as TDP-43 and TLS/FUS (58, –, 62)." (PMID 31263000, 2019). "Whether and how either up- or downregulation of FUS-dependent circRNAs contributes to ALS will be of major importance and could serve as an experimental blueprint for similar types of studies in other neurological disorders." (PMID 29116363, 2018). "The presented data support that FUS and TAF15 are more functionally related to each other, and that the FET-proteins have distinct functions in cellular signaling pathways which could have implications for the neurological disease pathogenesis." (PMID 23049996, 2012).
infection (16 papers, 2008 to 2025). The state of being infected such as from the introduction of a foreign agent such as serum, vaccine, antigenic substance or organism. "Infection of mice with the picornavirus Theiler’s murine encephalitis virus (TMEV) caused an ALS-like phenotype with cytoplasmic inclusions of TDP-43 and FUS in motor neurons and glial cells." (PMID 35925897, 2022). "Six days after infection, we observed a substantial amount of FUS-R521H-YFP aggregation within live neurons." (PMID 35082301, 2022). "Taken together, these results demonstrate that RABVΔG infection exacerbated the formation of aberrant SGs as well as the degeneration of SNs with mutant FUS, hallmarks of FUS-ALS pathogenesis." (PMID 31695598, 2019). "At day 2 post infection, control or FUS KO cells were sorted based on their GFP expression, and GFP(+) cells were further cultured to allow them to progressively enter latency, while monitoring their GFP expression at the indicated time post transduction." (PMID 31238957, 2019). "Chromatin immunoprecipitation analyses demonstrate that FUS is present at several KSHV lytic cycle genes during the latent stage of infection." (PMID 29986386, 2018). "The QTL position of qK1 for K+ concentration, total number of loci, candidate gene, and putative function was 39922192–39923794 bp, 16, LOC_Os01g68730 and RNA-binding protein FUS, putative, expressed, involved in cellular stress response, responses against pathogen infection, respectively." (PMID 37446320, 2023). "In addition, infection with two FUS shRNA lentivirus served to only decrease the expression of circPDE4B, whereas overexpressed FUS upregulated the expression of circPDE4B." (PMID 34039624, 2021). "We thus imaged SG marker TIAR and FUS-eGFP in neurons 2 days following infection with RABVΔG." (PMID 31695598, 2019). "Further, infection of cells or mice with enteroviruses or picornavirus TMEV induced the cytoplasmic aggregation of TDP-43 and/or FUS due to a compromised nuclear import mediated by viral proteins." (PMID 35925897, 2022). "The two- to fourfold lower read-out/exon ratios observed for two of the four genes (FUS and HNRNPA2B1) in Δvhs infection resulted from higher total RNA levels compared with wild-type HSV-1 infection reflecting the lack of vhs activity rather than reduced read-out36." (PMID 25989971, 2015).
movement disorder (3 papers, 2014 to 2021). Neurological conditions resulting in abnormal voluntary or involuntary movement, which may impact the speed, fluency, quality and ease of movement. "Compared with previously reported ALS6 cases, the prominent movement disorders were the characteristic features in both patients, indicating that FUS mutation can affect the function of movement coordinating system in addition to motor neuron degeneration." (PMID 32307925, 2020). "Apart from the typical ALS phenotype, patients with p.P525L mutation in the FUS gene can present with great clinical heterogeneity including multiple movement disorders." (PMID 32307925, 2020). "In this study, we describe two patients with FUS p.P525L mutation presenting with rapid progressive ALS and multiple movement disorders, which indicate the great clinical heterogeneity associated with FUS p.P525L mutation." (PMID 32307925, 2020). "The identification of a nonsense mutation in the NES domain of the FUS protein (p.Q290X) in a large kindred with autosomal dominant ET has raised interest in the role of these genes in this common movement disorder." (PMID 25375143, 2014). "Besides the typical ALS phenotype, patients with p.P525L mutation in the FUS gene can present with great clinical heterogeneity including multiple movement disorders." (PMID 32307925, 2020). "FUS proteinopathies include ALS cases with FUS mutations and three conditions presenting with FTD and/or a movement disorder, including atypical FTLD-U, neuronal intermediate filament inclusion disease, and basophilic inclusion body disease." (PMID 34539339, 2021).
blood cancer (1 paper, 2020). "The functional interaction between USP15 and FUS in blood cancer cells suggests that USP15 regulates DDR pathways in context-dependent manner." (PMID 33378683, 2020).
brain diseases (1 paper, 2022). "Additional pathways that lead to generation of aggresomes have not been determined for other proteins known to be involved in brain diseases, including hnRNPA1 and FUS." (PMID 35735914, 2022).